PAX6 (paired box 6)
Diseases named in the same sentence as PAX6 in open-access papers (continued):
Sharing a sentence is not in itself a finding about the gene and the disease.
aniridia (continued). "Loss of a single copy of Pax6/PAX6 results in a small eye phenotype in rodents and is the primary cause of the poly-symptomatic and progressive disease aniridia in humans." (PMID 30442116, 2018). "Our results of this study extended the pathogenic mutation spectrum of PAX6 for congenital aniridia and demonstrated the male germline chimerism by molecular experiments." (PMID 30334364, 2018). "The eye disease Aniridia is due in some cases to defects in the PAX6 gene defect associated with haploinsufficiency." (PMID 30542652, 2018). "The spectrum of symptoms associated with aniridia is due to haploinsufficiency of the paired box 6 gene (PAX6) and its role in the development and maintenance of the affected tissues." (PMID 30290306, 2018). "Our results extend the mutation spectrum of PAX6 and related clinical phenotypes, which has guiding significance for the diagnosis and prenatal diagnosis of congenital aniridia." (PMID 30334364, 2018). "Aniridia is a congenital disease that affects almost all eye structures and is primarily caused by loss-of-function mutations in the PAX6 gene." (PMID 29850208, 2018). "Although the intragenic PAX6 gene mutations are more common than microdeletions, in newborns affected with aniridia the analysis toward deletions is recommended first, due to the clinical importance of early WAGR syndrome identification." (PMID 29460221, 2018). "In the current study, we describe a novel disease-causing frameshift mutation (NM_000280.4(PAX6):c.565TC>T) in PAX6 in a 4-generation family affected with aniridia." (PMID 29850208, 2018). "Congenital aniridia is mainly associated with pathogenic variants in the PAX6 [OMIM:607108] gene, a master control gene for eye development, located on chr11p13." (PMID 30334364, 2018). "Fully heterozygous carriers of the nonsense PAX6 variants presented classical symptoms of congenital aniridia, including marked iris hypoplasia, photophobia, nystagmus, low visual acuity, as well as congenital or early-onset cataracts." (PMID 30386378, 2018). "Individual III-8 was found to carry a single PAX6 mutation presumably inherited from her mother, despite the reported history that both of her parents had aniridia." (PMID 29850208, 2018). "Low levels of Pax6 throughout development of heterozygous Pax6+/− mice cause small eyes, aniridia plus lens and corneal defects." (PMID 30290846, 2018). "In the two mosaic individuals carrying nonsense PAX6 mutations, similar levels of somatic mosaicism led to variable clinical outcomes ranging from congenital aniridia to considerably milder manifestations." (PMID 30386378, 2018). "PAX6 nonsense mutations been widely reported (p.Arg240X, p.W100X, p.R103X, etc.), and linked to aniridia with congenital cataract." (PMID 28450710, 2017). "In most of case, aniridia and related-syndromic conditions are caused by heterozygous loss-of-function defects in PAX6, located on chromosome 11p13." (PMID 28231309, 2017). "Solving those limitations is crucial for the correct diagnostic of deletions involving the PAX6 region in newborns with sporadic aniridia, in which a 11p13 deletion analysis should be prioritized to discard WAGR syndrome." (PMID 28231309, 2017). "This is best exemplified by point mutations in the human PAX6 gene leading to aniridia, while modulation of mouse Pax6 levels reduces cell proliferation and leads to CB and iris hypoplasia." (PMID 28250050, 2017). "Aniridia is most commonly correlated with PAX6 mutations;1,5 however, the number of catalogued mutations is continuously growing." (PMID 29238604, 2017). "A novel de novo mutation (c.225C>A; p.Tyr75*) was identified in the PAX6 gene in one family, and the same mutation was identified in an unrelated 2-year old girl with aniridia." (PMID 27463523, 2016). "Mammalian eye development is highly sensitive to the levels of Pax6 as haploinsufficiency causes aniridia in humans and multiple ocular defects in mice." (PMID 27918583, 2016).
aniridia (continued). "Early studies showed that the phenotypes of heterozygous Pax6+/− mice were similar to some human inherited conditions caused by PAX6 mutants, including aniridia and Peters’ anomaly." (PMID 27240603, 2016). "Extraocular disease is rare in PAX6-associated aniridia although structural brain anomalies and other sensory impairments have been identified." (PMID 27108798, 2016). "PAX6-associated aniridia is, however, a pan-ocular disease typified by foveal hypoplasia, cataracts, and progressive corneal opacification in addition to the iris anomaly." (PMID 27108798, 2016). "The majority (92%) of mutations identified to be associated with aniridia in the PAX6 gene includes; one or two base pair deletions and insertions resulting a change in the reading frame of the protein, nonsense, and splice site mutations." (PMID 27463523, 2016). "A novel de novo variant (c.225C>A; p.Tyr75*) was identified in the PAX6 gene in two unrelated probands with aniridia." (PMID 27463523, 2016). "Almost all cases of classical aniridia associated with PAX6 haploinsufficiency present with foveal hypoplasia." (PMID 27124303, 2016). "Pax6 mutations are responsible for aniridia, while Pax6 overexpression is associated with retinoblastoma cancer progression through promotion of proliferation and cell survival." (PMID 25695251, 2015). "In humans, heterozygous mutations in Pax6 have been found in patients with aniridia, iris hypoplasia, corneal opacification, autosomal dominant keratitis and isolated foveal hypoplasia." (PMID 26262640, 2015). "Human PAX6 mutations are associated with severe ocular disorders such as aniridia, Peters anomaly and chronic limbal stem cell insufficiency." (PMID 25692557, 2015). "All participants in the aniridia group had a confirmed clinical diagnosis of aniridia and 8 out of 12 had confirmed heterozygous loss-of-function mutations within the coding region of the PAX6 gene." (PMID 25566032, 2014). "Congenital aniridia is a rare condition (incidence between 1 : 64000 and 1 : 100000) that typically affects both eyes and is associated with PAX6 gene mutations." (PMID 27355034, 2014). "Heterozygous null mutations within PAX6, cytogenetic deletions of chromosome 11p13 that encompass PAX6 or chromosomal rearrangements that prevent PAX6 expression from one allele are all causal for aniridia." (PMID 25566032, 2014). "Heterozygous human PAX6 mutations can result in aniridia and in a variety of structural brain abnormalities that closely resemble those seen in Small eye (sey) mice heterozygous for Pax6 mutations." (PMID 24488179, 2014). "PAX6 mutations can also be associated with aniridia, optic nerve hypoplasia and brain abnormalities." (PMID 24688117, 2014). "In summary, we identified a 7 year old male with aniridia and congenital fibrosis of the extraocular muscles as a result of independent mutations in the PAX6 and KIF21A genes, inherited independently from his father and mother." (PMID 23799907, 2013). "Ocular coloboma and aniridia are allelic disorders related to heterozygous mutations in the paired box gene 6 (PAX6)." (PMID 24349436, 2013). "This increased epithelial fragility suggests that cell loss is likely to be abnormally high in people with PAX6+/− aniridia as well as heterozygous Pax6+/− mice." (PMID 23967157, 2013). "The deletion mutation (c.112delC) in the PAX6 gene was first identified in a Chinese family with aniridia, congenital progressive cataract, developmental delay, or the absence of ulna." (PMID 23734086, 2013). "The location is consistent with this mutation’s presence for the first time in PAX6 of patients with aniridia." (PMID 23734086, 2013). "The pair box 6 (PAX6) gene located at 11p13 has been confirmed as the major gene associated with aniridia." (PMID 23734086, 2013). "This study is to summarize the phenotypes and identify the underlying genetic cause of the paired box 6 (PAX6) gene responsible for aniridia in two three-generation Chinese families in northern China." (PMID 23734086, 2013).
aniridia (continued). "Humans who are heterozygous for mutations in PAX6 suffer from congenital aniridia and brain defects while homozygous mutations in PAX6 are incompatible with life." (PMID 24223221, 2013). "According to the Human PAX6 Allellic Variant Database, some PAX6 mutations have been reported to be associated with aniridia accompanied by congenital cataract." (PMID 23734086, 2013). "The mutation (c.362C>T, p.Ser121Leu) in the PAX6 gene was first identified in a patient with aniridia with congenital ptosis." (PMID 23734086, 2013). "He inherited the c.2860C > T (p.Arg954Trp) mutation in KIF21A from his mother, who also had CFEOM1, and the c.745delC (p.Leu249TyrfsX22) mutation in PAX6 from his father who had congenital aniridia." (PMID 23799907, 2013). "In summary, this study identified a PAX6 mutation first reported in northern Chinese patients with aniridia." (PMID 23734086, 2013). "In summary, this study identified one mutation of PAX6 first reported in northeastern Chinese patients with aniridia." (PMID 22815628, 2012). "In this study, we found two mutations—one in each of the two exons of the PAX6 gene—that are associated with aniridia: c.375_376delAG and c.868_871dupAGTT." (PMID 22919266, 2012). "The pair box gene 6 (PAX6) located at 11p13 is confirmed to be the major gene associated with aniridia." (PMID 22393272, 2012). "According to the Human PAX6 Allellic Variant Database, over 60 PAX6 mutations have been reported to be associated with aniridia accompanied with congenital cataract." (PMID 22393272, 2012). "Haplo-insufficiency at the paired box gene 6 (PAX6) locus causes aniridia,which is characterized by iris hypoplasia and other anterior and posterior eye defects leading to poor vision." (PMID 22815628, 2012). "Although PAX6 mutations and polymorphisms have been reported in various ethnic groups, we report, for the first time, the identification of one new PAX6 mutation in Chinese aniridia patient." (PMID 22919266, 2012). "Our study first identified of the PAX6 c.307C>T mutation in a large pedigree with aniridia and congenital progressive cataract." (PMID 22393272, 2012). "Deletions distal to PAX6 have previously been shown to cause aniridia and are thought to inhibit the expression of the associated PAX6 allele due to changes in the local chromatin structure." (PMID 22912880, 2012). "The molecular bases for aniridia are derived from mutations of PAX6 that lead to premature protein termination." (PMID 22815628, 2012). "There are several examples of such mutated sequences in both ocular and systemic diseases, with regulatory mutations 3′ to PAX6 causing aniridia and demonstrated to be functionally relevant by murine transgenesis rescue experiments." (PMID 22690109, 2012). "Aniridia is a human eye malformation caused by heterozygous null mutations of PAX6, which is extraordinarily conserved throughout evolution." (PMID 22815628, 2012). "In conclusion, most of the mutations identified in Korean aniridia patients lead to the premature truncation of the PAX6 protein, supporting that haploinsufficiency of the PAX6 protein causes the classic aniridia phenotype." (PMID 22393275, 2012). "Among those genes, PAX6 is the most prominent; it is the only known causative gene in classic aniridia and accounts for approximately 80% of these patients." (PMID 23213277, 2012). "In summary, this study identified one novel mutation of PAX6 in one Chinese sporadic patient with aniridia." (PMID 22919266, 2012). "Most of the mutations identified in Korean aniridia patients lead to the premature truncation of the PAX6 protein, supporting that PAX6 protein haploinsufficiency causes the classic aniridia phenotype." (PMID 22393275, 2012). "It is known that mutations in the transcription factor PITX2 and FOXC1 genes lead to ARS, while mutations of the PAX6 gene underlies many cases of aniridia." (PMID 21617748, 2011).
aniridia (continued). "The classic aniridia phenotype in Saudi Arabia is typically caused by heterozygous PAX6 mutations, even in the setting of enhanced homozygosity from recent shared parental ancestry." (PMID 21423868, 2011). "One proband (QT634) had a full iris, but his father harbored the same heterozygous PAX6 mutation and had complete aniridia." (PMID 21850189, 2011). "Previous studies have shown that dominant PAX6 mutations are the only known cause of classic aniridia." (PMID 21423868, 2011). "In this series of classic aniridia in mostly consanguineous families from Saudi Arabia, the heterozygous PAX6 mutation was detected in 4/4 familial cases and 6/8 sporadic cases." (PMID 21423868, 2011). "The 566 kb hemizygous deletion of chromosome 11p13 downstream of PAX6 should be the cause of the familial aniridia in this Chinese family, although two copies of PAX6 are intact." (PMID 21321669, 2011). "Aniridia is an autosomal dominant disorder resulting almost exclusively from mutations in the PAX6 gene." (PMID 21633710, 2011). "In this study, both cycle sequencing and MLPA were used to detect mutations in the PAX6 gene of 33 Chinese probands with aniridia." (PMID 21850189, 2011). "The mutation frequency of PAX6 in Chinese aniridia patients is similar to that in Caucasian aniridia patients." (PMID 21850189, 2011). "In humans, mutations in PAX6 have been demonstrated in several patients with aniridia, a panocular disease that is associated with iris hypoplasia, corneal opacification, cataract, foveal dysplasia, and other diseases." (PMID 21655361, 2011). "Whereas mutations or intragenic deletions of PAX6 represent the major causes of aniridia, genomic rearrangements involving the downstream region of PAX6 were identified in patients with aniridia although both copies of PAX6 are intact in these patients." (PMID 21321669, 2011). "Mutations in PAX6 can lead to varieties of autosomal-dominant ocular malformations with aniridia as the major clinical signs." (PMID 21321669, 2011). "PAX6 mutations have been identified in sporadic aniridia cases from different populations as well as in familial aniridia cases." (PMID 21655361, 2011). "In summary, this study identified two novel mutations of PAX6 in a Chinese family and a sporadic patient with aniridia." (PMID 22171157, 2011). "In this study, we found two mutations, one in each of the two exons of PAX6 that are associated with aniridia: c.891delA and c.607C>T." (PMID 22171157, 2011). "Heterozygous disruptions in the PAX6 gene cause the human eye malformation aniridia and the mouse smalleye (Sey) mutation demonstrating dosage sensitivity." (PMID 22220192, 2011). "In the present paper we report the finding of a novel PAX6 mutation in an Indian family with aniridia." (PMID 21633710, 2011). "Both of these mutations were previously reported in patients with aniridia (The Human PAX6 Mutation Database)." (PMID 20806047, 2010). "A novel deletion mutation in the PAX6 gene was identified in a Chinese family with aniridia and congenital cataract." (PMID 20664694, 2010). "PAX6 plays a major role in the organization of the developing eye, and various heterozygous mutations in PAX6 have been identified in patients with aniridia." (PMID 20664694, 2010). "In human, haploinsufficiency of PAX6 causes the absence or hypoplasia of the anterior commissure, decreased volumes of the corpus callosum and smaller brain size, in addition to aniridia and various eye abnormalities." (PMID 21203536, 2010). "This study identified a novel deletion mutation of PAX6 in a Chinese family with aniridia and congenital cataract." (PMID 20664694, 2010). "Recent studies have identified PAX6 mutations in individuals who manifest mental retardation, aniridia and autism." (PMID 21203536, 2010). "Of the 31 patients with the p.Arg240X mutation reported in the Human PAX6 Mutation Database, 26 have isolated aniridia while the remaining five have associated ocular anomalies (four with cataract)." (PMID 20806047, 2010).
aniridia (continued). "A recent review of PAX6 mutations in the Human PAX6 Mutation Database found that mutations which lead to a premature termination codon are generally associated with aniridia while missense mutations typically result in other related ocular phenotypes." (PMID 20806047, 2010). "Mutations in PAX6 have been shown to result in aniridia, a congenital ocular condition which presents with abnormalities including iris hypoplasia, corneal opacities, cataracts, and foveal and optic nerve hypoplasia." (PMID 20360993, 2010). "Two patients with Gillespie-like syndrome (iris hypoplasia/aniridia, tremor/ataxia, and learning disability/mental retardation) were also found to have mutations in PAX6." (PMID 20806047, 2010). "In this study, we analyzed the coding sequences of PAX6 in a large Chinese family and identified a novel frameshift mutation that causes aniridia and cataract." (PMID 20664694, 2010). "Familial congenital aniridia is a hereditary disease transmitted in an autosomal dominant fashion and is caused by genetic defects within the paired box 6 (PAX6) gene in about 90% of cases." (PMID 20500513, 2010). "In that study, the c.608G>A variation in SIX6 was detected in an individual with typical congenital aniridia and a previously determined PAX6 mutation (c.718C>T, p.R240X)." (PMID 20057906, 2009). "Our detection rate is comparable with previous reports that 30%–80% of patients with aniridia have PAX6 mutations." (PMID 19898691, 2009). "Mutations in the Paired Box gene 6 (PAX6) located on chromosome 11p13 have been shown to cause aniridia." (PMID 19862335, 2009). "Haploinsufficiency or dominant negative mutation of PAX6 leads to aniridia, congenital cataract, Peter’s anomaly, Gillespie syndrome, and midline fusion defects, while complete deficiency of PAX6 leads to anophthalmia." (PMID 19898691, 2009). "There were eight reports, four in English and four in Chinese, each mentioned a PAX6 mutation in one Chinese family with aniridia." (PMID 19898691, 2009). "Both novel and known PAX6 mutations were identified in the current study, and PAX6 mutations were closely associated with aniridia." (PMID 19898691, 2009). "Most PAX6 nonsense mutations lead to aniridia, while missense mutations are related to foveal hypoplasia, congenital cataracts, or anterior segment anomalies." (PMID 19898691, 2009). "We report three PAX6 mutations segregating in three families with aniridia originating from the northwestern part of Egypt." (PMID 19862335, 2009). "A frequently updated summary of PAX6 mutations, which are associated with aniridia and related disorders, is documented at the PAX6 allelic variation database." (PMID 18483559, 2008). "Paired box gene 6 (PAX6) heterozygous mutations are well known to cause congenital non-syndromic aniridia." (PMID 18776953, 2008). "In the present study, we further analyze PAX6 variants in a group of Mexican aniridia patients and describe associated ocular findings." (PMID 18776953, 2008). "Mutations in the PAX6 gene have been implicated in aniridia, a congenital malformation of the eye with severe hypoplasia of the iris." (PMID 18483559, 2008). "We present here a de novo and novel PAX6 frameshift mutation that causes aniridia in an Ashkenazi-Jewish family." (PMID 18334930, 2008). "A recent genotype-phenotype correlation analysis of 286 pathogenic PAX6 mutations revealed that mutations that introduce a premature termination codon into the open reading frame are predominantly associated with aniridia." (PMID 18334930, 2008). "We studied PAX6 mutations in a large spectrum of patients who presented with aniridia phenotypes, Peters' anomaly, and anterior segment malformations associated or not with neurological anomalies." (PMID 17417613, 2007). "As a result, we have excluded a large deletion in PAX6 as a cause of aniridia in the Catalan sheep dog." (PMID 17417604, 2007).